MIR198 (microRNA 198)
Synonyms: hsa-mir-198; MIRN198; miR-198
Gene: MicroRNA gene on chromosome 3 (120,395,668 to 120,395,729, reverse strand). Ensembl gene ENSG00000284121.
Gene Ontology:
Biological process: miRNA-mediated post-transcriptional gene silencing
Cellular component: RISC complex
Diseases named in the same sentence as MIR198 in open-access papers:
MIR198 is named in the same sentence as 1 disease in open-access papers, as found by Europe PMC text mining. Sharing a sentence is not in itself a finding about the gene and the disease.
MIR198 shares sentences with these, for which no sentence is quoted: head and neck squamous cell carcinoma (1 paper).